MMP9 (matrix metallopeptidase 9)
Diseases named in the same sentence as MMP9 in open-access papers (continued):
Sharing a sentence is not in itself a finding about the gene and the disease.
TB meningitis (10 papers, 2009 to 2025). "MMP-9 level was significantly greater in cerebrospinal fluid (CSF) of meningeal TB which associates with their neurological compromise." (PMID 34350132, 2021). "For an example, in case of tuberculous meningitis, increased MMP-9 expression is linked to tissue destruction, a pathological hallmark of inflammatory host immune response." (PMID 19290049, 2009). "Another specific MMP-9 inhibitor, SB-3CT, has also shown beneficial activity combined with the same standard antibiotics, but in a mouse model of TB meningitis." (PMID 40431213, 2025). "In humans, MMP-9 was highly expressed in tuberculous meningitis (TBM) and pleural TB, both diseases that manifest themselves by extensive tissue destruction." (PMID 34745105, 2021). "The levels of MMP-9 were elevated in the cerebrospinal fluid of TB meningitis patients and pleural fluid." (PMID 32218787, 2020). "MMP-9 concentrations are increased in the cerebrospinal fluid of patients with TB meningitis and correlate with extent of neurological compromise." (PMID 30045688, 2018). "While earlier studies had found that MMP9 levels are elevated in tuberculous meningitis, very few studies have looked at the relation between the elevated MMP9 levels and treatment outcome in patients with tuberculous meningitis." (PMID 28704492, 2017). "Tuberculous meningitis is characterized by elevated levels of matrix metalloproteinase 9 (MMP9) in the cerebrospinal fluid (CSF)." (PMID 28704492, 2017). "There are only a handful of published studies on MMP9 levels in patients with tuberculous meningitis." (PMID 28704492, 2017). "MMP-9 plays a prominent role in progression of tuberculous meningitis from initial to advanced stages." (PMID 27899068, 2016). "However, dexamethasone administration had an inhibitory effect on bacillary clearance, while SB-3CT potentiated the bacillary clearance, suggesting that specific inhibition of MMP-9 can be more beneficial in the management of TB meningitis." (PMID 40431213, 2025). "Moreover, NICD1, Hes1, and MMP9 levels were increased in brain tissue samples from patients with tuberculosis meningitis." (PMID 29867921, 2018). "Thus, taken together, available evidence on the relation between MMP9 levels and treatment outcome in tuberculous meningitis is equivocal." (PMID 28704492, 2017). "We tested the hypothesis that pretreatment MMP9 levels in the CSF would be higher in tuberculous meningitis patients experiencing a poor treatment outcome." (PMID 28704492, 2017). "Hence, further studies are warranted to justify a clinical trial of MMP9 inhibitors as adjunctive treatment in tuberculous meningitis, which remains the most lethal form of TB." (PMID 28704492, 2017). "One possible explanation for the lack of association between MMP9 levels and treatment outcome could be that not all deaths in tuberculous meningitis are attributable to CNS inflammation." (PMID 28704492, 2017). "Therefore, we conducted the present study to test the hypothesis that pretreatment CSF levels of MMP9 would be higher in tuberculous meningitis patients with unfavorable treatment outcome." (PMID 28704492, 2017). "However, the association of higher MMP9 levels with better GCS scores suggests a possibility that MMP9 inhibition could be counterproductive, since altered consciousness is an important prognostic factor in tuberculous meningitis." (PMID 28704492, 2017). "MMP-9 levels were 0.62 ± 0.40 ng/ml for controls, 9.0 ± 0.87 ng/ml for stage I, 12.0 ± 1.34 ng/ml for stage II and 16.86 ± 2.7 ng/ml for stage III tuberculous meningitis patients." (PMID 27899068, 2016). "We found that tuberculous meningitis patients with a poor treatment outcome did not have higher MMP9 levels in the CSF at baseline." (PMID 28704492, 2017). "Further, MMP9 levels in the CSF did not correlate with blood-brain barrier permeability in patients with tuberculous meningitis." (PMID 28704492, 2017).
TB meningitis (continued). "Our findings do not support the hypothesis that pretreatment levels of MMP9 would be higher in tuberculous meningitis patients experiencing a poor treatment outcome." (PMID 28704492, 2017). "MMP9 plays an important role in macrophage recruitment, and destruction of extracellular matrix by MMPs could damage the blood-brain barrier (BBB) in patients with tuberculous meningitis." (PMID 28704492, 2017). "Levels of MMP-9 were not apparently affected with antitubercular drugs only indicating that antitubercular drugs are not involved in reducing inflammation in tuberculous meningitis patients which explains the life-long neurological defects even after bacillary clearance." (PMID 27899068, 2016). "In this study, the levels of MMP-9 and its inhibitor, TIMP-1 (tissue inhibitor of metalloproteinases-1), were screened using zymography and reverse zymography in cerebrospinal fluid and serum of tuberculous meningitis patients at different stages of the disease." (PMID 27899068, 2016).
breast adenocarcinoma (9 papers, 1998 to 2026). "In experiments by Moller, conditioned media from mammary adenocarcinoma cell lines significantly increased expression of MMP9 in fibroblasts." (PMID 29581841, 2018). "In vitro, these rats’ mammary adenocarcinoma cells expressed lower matrix metalloproteinases-9 (MMP-9), transforming growth factor-beta (TGF-β), and tumour necrosis factor alpha (TNF-α) levels after CAM treatment." (PMID 25729426, 2015). "LPA increases MMP-9 mRNA expression in breast adenocarcinoma cells, and we have recently demonstrated that MMP-9 catalyzes E-cadherin ectodomain shedding in EOC cells." (PMID 22593767, 2012). "Conversely, in rats bearing matrix metalloproteinase-9 (MMP-9) producing 13762NF mammary adenocarcinoma (MTLn3 clone), polyuria occurred chiefly during the first 24 h after CY treatment." (PMID 9792146, 1998). "On the contrary, inhibition of ERK signalling pathway might result in decreased expression of MMP‐2 and MMP‐9 in human breast adenocarcinoma cells." (PMID 27491646, 2017). "Indeed, TLR4 induces the expression of T-LAK cell-Originated Protein Kinase (TOPK) that has been proposed to regulate MMP-9 gelatinase expression and activity, thus acting as key mediator of ET-induced migration and invasion of human breast adenocarcinoma cell lines." (PMID 34868543, 2021).
Chronic colitis (9 papers, 2017 to 2025). A chronic inflammatory disease of the large intestine (colon, cecum and rectum). "A higher number of infiltrated neutrophils and more ulcerative lesions in humans with chronic colitis could be the possible reasons for the higher active MMP-9 activities in humans." (PMID 29530095, 2018). "Parameters of chronic colitis are similar in wild type and MMP-9 knockout mice." (PMID 28561062, 2017). "Given the hub position of Mmp9 and Timp1 and the formation of a highly connected cluster of MMPs in the core gene-retrieved network, the changes in the MMPs profile can be involved in the regulation of malignant transformation of colon tissue during chronic colitis." (PMID 36901742, 2023). "We used qRT-PCR analysis to test the expression of MMPs known to be regulated in CD and showed that MMP-9 and MMP-2 were upregulated, but TIMP-1 was downregulated after the TFA treatment in the TNBS-induced chronic colitis mice model." (PMID 35002710, 2021). "We found that colon MMP-9 activity was absent in the CT group while chronic colitis induced its activity." (PMID 34301970, 2021).
chronic lung disease (9 papers, 2012 to 2025). According to the definitions of the American and British Thoracic Societies, including pulmonary functional tests, X-rays, and CT scans for items such as fibrosis, bronchiectasis, bullae, emphysema, nodular or lymphomatous abnormalities. "Inappropriate expression and excessive activity of several matrix metalloproteinases (MMP), including MMP-9 has been implicated in the tissue destructive processes associated with chronic lung diseases including COPD." (PMID 27234393, 2013). "Abundant proteobacteria increase MMP-9 and contribute to tissue proteolysis followed by neutrophil recruitment, lung tissue injury, and perpetuation of chronic lung disease." (PMID 36363728, 2022). "It is well known that the expression and secretion of MMP-9 in chronic lung diseases is regulated by various stimuli, including IL-1β, TNF-α, and LPSs." (PMID 32829707, 2020). "Dose-dependent cleavage of SP-D by MMP-9 using levels of protein similar to that observed in patients with chronic lung disease suggests in vivo relevance for this cleavage event." (PMID 22860023, 2012). "As our group and others have previously shown, increased proteobacteria in the lungs can upregulate the activity of matrix metalloproteinase 9 (MMP-9), leading to progressive lung tissue damage and the development of chronic lung diseases." (PMID 36363728, 2022). "TIMP1 is an inhibitor of Matrix metallopeptidase 9 (MMP9), which plays an important role for variety of homeostatic functions and elicit repair responses as balance mechanisms in many chronic lung diseases like COPD." (PMID 29716632, 2018). "In chronic lung disease, patients with COPD display significantly higher serum MMP-9 and elevated MMP-9/TIMP-1 ratios, which correlate negatively with lung-function parameters such as FEV1 and FEV1/FVC, underlying the role of MMP-9 in airway remodeling and functional decline." (PMID 41304763, 2025).
HCMV infection (9 papers, 2010 to 2022). "Studies show that a productive HCMV infection reduced MMP9 activity in human macrophages, a finding that was associated with immediate early or early gene expression of HCMV." (PMID 25573478, 2015). "We also found an increase in the secretion of MMP3 and MMP9 at 9 days post HCMV infection that we propose would aid the virus in tissue dissemination from infected pericytes as it traffics through the inner retinal barrier." (PMID 25573478, 2015). "Moreover, HCMV infection alters the MMP-9/TIMP-1 balance in macrophages through immediate-early (IE) gene and late viral gene expression." (PMID 35847899, 2022). "Cytomegalovirus infection also inhibited migration of EVTs and resulted in a significant reduction in MMP-2 and MMP-9 expression compared with uninfected EVTs." (PMID 33374185, 2020). "In particular, HCMV infection led mainly to the over-expression of CCL2, CCL3, CCL11, CXCR4, IL-1β, IL13, MMP1, MMP3, MMP9 and MMP13, SERPINA1, TNFα, and BMP7, and the gradual and constant downregulation of IL13RA2 (up to almost 800-fold at 14 days p.i.)." (PMID 32899126, 2020). "A reduction in MMP-9 mRNA, protein, and activity levels but increased tissue inhibitor of matrix proteinases (TIMP)-1 mRNA and protein levels was found after HCMV infection." (PMID 25452935, 2014). "After 48 h, it is observed that villus HCMV infection condition and the c-erbB-2, MMP-2 and MMP-9's expression levels in villus and characteristics of space distribution change." (PMID 21392403, 2011).
hyperhomocysteinemia (9 papers, 2016 to 2025). A serious metabolic condition caused by mutations in the MTHFR gene, medications, or nutritional deficiency. "Hyperhomocysteinemia (HHcy) is associated with inflammation and a rise in the expression of matrix metalloproteinase-9 (MMP-9) in the vascular wall." (PMID 27349749, 2016). "Hyperhomocysteinemia (HHcy) is known for causing inflammation and vascular remodeling, particularly through production of reactive oxygen species (ROS) and matrix metalloproteinase‐9 (MMP‐9) activation." (PMID 29595876, 2018). "Hydrogen sulfide reduces the increase in blood-brain barrier permeability induced by hyperhomocysteinemia by inhibiting MMP-9." (PMID 40868017, 2025).
memory impairment (9 papers, 2013 to 2023). "The higher serum Cathepsin D, IgE, EGFR, MMP-9, vWF, haptoglobin, and p-Tau181 levels were associated with severity of memory impairment (as indicated by lower MMSE and MoCA scores, and higher ADL, CDRglobal, and CDRsob scores)." (PMID 35769604, 2022). "Herein, the decrease of MMP-9 in the HPP can be correlated with memory impairment observed in the mephedrone-treated rats during reconsolidation of fear conditioning." (PMID 36768263, 2023). "Since MMP-9 plays an important role in learning and memory impairment after anesthesia/surgery, we questioned where the increased MMP-9 came from." (PMID 35273488, 2022). "Mmp-9 heterozygous mice exhibited learning and memory impairments, reflected by a significant decrease in preference to explore the object in a novel location (individual t-test, p < 0.05), compared with the familiar location." (PMID 31555105, 2019). "Second, we also showed that MMP9 might contribute to the age-dependent learning and memory impairment." (PMID 28881691, 2017). "Therefore, the down-regulation of MMP-9 upon vitamin B6 treatment indicates a long-term effect of vitamin B6 in terms of reduced learning and memory impairments." (PMID 23977941, 2013). "In addition, the ceiling effect of learning and memory impairment in these elderly MMP9-/- mice may confront the interpretation of the results." (PMID 28881691, 2017). "Explaining the lack of a reminder-specific effect of doxycycline in the present data (but not global memory impairment), there is a possibility that MMP-9 is involved in consolidation, explaining our previous result, but not in reconsolidation." (PMID 31615840, 2019).
Miscarriage (9 papers, 2010 to 2023). A pregnancy that ends at a stage in which the fetus is incapable of surviving on its own, defined as the spontaneous loss of a fetus before the 22th week of pregnancy. "Other studies showed that increasing MMP9 and the MMP2/TIMP 2 ratio increased the risk of miscarriage." (PMID 36910123, 2022). "AIT inhibits ERK/MMP-2 and MMP-9 pathways through PD-L1 reduction, attenuates embryonic trophoblast invasion and ultimalely induces miscarriage ultimately." (PMID 31656199, 2019). "We believe TFSC can promote the migration and invasion of EVT cells by increasing MMP9 expression, and prevent miscarriage by activating Notch, AKT, and MAPK signaling pathways." (PMID 30478366, 2018). "In addition, using anti-inflammatory medication such as lactoferrin was able to prevent miscarriage/abortion by modulating MMP-9/TIMP-1 ratio and promoting repair." (PMID 35622593, 2022). "AUB women with miscarriage history showed upregulation in MMP2, TGFB3 (P < 0.05), and downregulation in MMP9 and VEGFB (P < 0.05) expression compared to AUB group with no miscarriage history." (PMID 36564776, 2022). "Given its potential clinical benefit on preventing miscarriage, this study aims at examining the therapeutic effect of TFSC in the prevention of premature birth by upregulating MMP9 and promote EVT cell invasion." (PMID 30478366, 2018). "In contrast, expression of MMP9 (0.21 ± 0.03) and VEGF (0.10 ± 0.02) decreased significantly (P < 0.05) in AUB females with miscarriage compared to AUB females with no (0.39 ± 0.06, 0.19 ± 0.01) miscarriage history." (PMID 36564776, 2022). "Recent studies have reported that these flavonoids can promote the migration and invasion of extravillous trophoblast cells by increasing matrix metalloproteinase 9 (MMP9) expression and prevent miscarriage by activating Notch, AKT, and mitogen-activated protein kinase (MAPK) signaling pathways." (PMID 35734397, 2022).
myopia (9 papers, 2011 to 2024). "The intricate interplay between THBS1, TGF-β1, and MMP9 within the context of scleral remodeling demands more extensive exploration to unravel the mechanisms that underlie myopia development." (PMID 38355399, 2024). "The study sought to investigate the effect of the Insulin-like growth factor-1 (IGF-1) and Matrix metalloproteinase-9 (MMP-9) genes polymorphisms on high myopia in a Han population of China." (PMID 35647299, 2022). "As for the association between MMP-9 (also known as gelatinase B) and myopia, few previous reports were found." (PMID 32596291, 2020). "There have been two SNPs rs3025058 (MMP3) and rs17576 (R279Q; MMP9) previously associated with myopia." (PMID 23077567, 2012). "Our findings indicated that rs2236416 of MMP-9 was associated with myopia in the population." (PMID 35647299, 2022). "The study explored the association between the SNPs (rs5742632, rs10860860, rs17576, and rs2236416) of IGF-1 and MMP-9 and high myopia in a Han population." (PMID 35647299, 2022). "In the case of common myopia there has been one study in a Caucasian cohort that assessed selected SNPs in MMP1, MMP3 and MMP9 and found a positive association of myopia with the rs3025058 in MMP3 (p = 0.015) and the rs17576(R279Q) in MMP9 (p = 0.026)." (PMID 23077567, 2012). "MMP-9 rs2236416 is interrelated to myopia in the population, suggesting that the MMP-9 gene locus may play a role in myopia." (PMID 38660258, 2024). "Thus, LF administration inhibited LIM-induced proteolytic activity of MMP-2 and MMP-9, followed by the suppression of myopia development." (PMID 33291388, 2020). "Initial findings indicated that the best p values for each trait were 0.02 for myopia at rs2274755 (MMP9), 0.02 for SE at both rs3740938 (MMP8) and rs131451 (MMP11), 0.01 for axial length at rs11225395 (MMP8), 0.01 for anterior chamber depth at rs498186 (MMP1) and 0.02 at rs10488 (MMP1)." (PMID 23077567, 2012). "These are in MMP2 for refractive error and in MMP3 and MMP9 for common myopia." (PMID 23077567, 2012). "The result suggested MMP-9 gene locus may play a role in myopia." (PMID 35647299, 2022). "MMP-9 concentrations also differed depending on DR staging, DM duration, PRP treatment, and degree of axial myopia." (PMID 27467659, 2016). "Estrogen has been shown to upregulate MMP-2 and/or MMP-9 in human ocular cells, and MMP-2 upregulation was suggested as part of the scleral remodeling process in myopia development." (PMID 21921981, 2011).